NLRP3 (NLR family pyrin domain containing 3)
Diseases named in the same sentence as NLRP3 in open-access papers (continued):
Sharing a sentence is not in itself a finding about the gene and the disease.
psoriasis (continued). "Due to the difficulty of obtaining skin samples from clinical patients, the number of psoriasis patients used to verify the skin expression levels of NLRP3 and IL-1β was relatively small." (PMID 41383588, 2025). "Studies have shown that the NLRP3 inflammasome is also involved in other skin diseases, such as psoriasis, urticaria, and bullous pemphigoid." (PMID 41178942, 2025). "For example, IL1B activates the NLRP3 inflammasome which promotes the secretion of inflammatory factors such as IL-17 and IL-23, which play a key role in the inflammatory response in psoriasis." (PMID 40898481, 2025). "Research has indicated that the inflammasome inhibitor (NLRP2/AIM-3-IN-21) exhibited significant therapeutic potential in psoriasis, and effectively suppressed the expression levels of NLRP3, IL-17A, and AIM2 in psoriatic skin lesion tissues." (PMID 41383588, 2025). "Reduced PGGT1B levels can increase the expression of CDC42, which further activates NLRP3 inflammation in macrophages through NF-κB signaling, further aggravating the inflammatory state of psoriasis." (PMID 40430037, 2025). "A possible mechanism for this is that PGGT1B-deficient macrophages migrate to the epidermis more easily during psoriasis, which leads to the activation of Cdc42, NF-κB signaling, and NLRP3 inflammatory corpuscles." (PMID 40430037, 2025). "It is well documented that the activation of NLRP3 inflammasome is essential for pyroptosis in various diseases, psoriasis is also included." (PMID 38967379, 2024). "Immunohistochemical studies in mouse models of psoriasis have also confirmed that NLRP3 expression levels are significantly higher than those in control groups." (PMID 39595526, 2024). "Currently, the only available option for inhibiting NLRP3-mediated effectors in clinical practice in both HS and psoriasis is drugs targeting IL-1β, like anakinra and canakinumab." (PMID 38248345, 2024). "In the psoriatic mouse model, 3‐BrPA improves imiquimod‐induced psoriasis‐like dermatitis by downregulating NF‐κB and NLRP3 activation." (PMID 39623879, 2024). "Pyroptosis mediated by NLRP3/Caspase‐1/GSDMD pathway has been viewed as a participator in psoriasis." (PMID 38967379, 2024). "There was a statistically significant difference in disease severity among psoriasis patients based on their NLRP3 genotypes (P < 0.001)." (PMID 38965465, 2024). "For example, a previous study reported that NLRP3 inflammasome-mediated pyroptosis was present in IMQ-induced psoriasis, similar to skin inflammation in mice." (PMID 38125299, 2024). "Cycloastragenol inhibits NLRP3 inflammasome-mediated pyroptosis in macrophages to relieve imiquimod-induced psoriasis-like skin inflammation in mice." (PMID 38429819, 2024). "Here, our research was to illuminate the impacts of Wogonin on the progression of psoriasis and further delve into the mechanism of Wogonin related to NLRP3 inflammasome." (PMID 38967379, 2024). "Levels of serum CRP and TNFα in NLRP3 genotypes of psoriasis patients were significantly different (P < 0.00001)." (PMID 38965465, 2024). "The NLRP3 inflammasome is involved in the pathophysiology of various skin diseases, such as psoriasis, urticaria, and bullous pemphigoid." (PMID 39684233, 2024). "In an IMQ-induced psoriasis mouse model, D3T treatment notably reduced ear thickness, skin redness, scaling, and the expression of KI-67, the NLRP3 inflammasome, and cleaved caspase-1 in skin samples." (PMID 38892253, 2024). "Skin samples from psoriasis patients showed that the NLRP3 inflammasome was expressed at a level four times higher than in normal skin." (PMID 39337637, 2024). "Regarding disease severity in psoriasis patients, there was statistically significant difference among NLRP3 genotypes (P < 0.001)." (PMID 38965465, 2024).
psoriasis (continued). "The mechanistic study reveals that D3T exerted these effects by inhibiting the JNK pathway and highlights the potential of D3T as a promising agent for psoriasis treatment by targeting NLRP3 inflammasome activation." (PMID 38892253, 2024). "Unfortunately, the current possibilities of blocking pyroptosis and NLRP3 activation in psoriasis and HS are very limited and show ambiguous efficacy." (PMID 38248345, 2024). "Recent new insights into the pathogenesis of psoriasis have increased the attention given to inflammatory cell death, including NLRP3-mediated pyroptosis, caspase-mediated apoptosis, and RIP-mediated necroptosis." (PMID 38125299, 2024). "The use of drugs that inhibit NLRP3 and/or caspase-1 activation, such as metformin and ginsenoside Rg1, has shown a positive effect in the treatment of psoriasis-like lesions by inhibiting Il1b and keratinocyte proliferation." (PMID 37564649, 2023). "Although we demonstrated the treatment effect of D3T on reducing NLRP3 inflammasome activation in IMQ-induced psoriasis and the keratinocyte cell line, there are still some limitations to this study." (PMID 37686332, 2023). "In this study, we demonstrated the effects of D3T on inhibiting NLRP3 inflammasome activation in the treatment of psoriasis through in vivo and in vitro experiments." (PMID 37686332, 2023). "Amongst these different inflammasomes, the NLRP3 inflammasome has been reported as having an expression that was 3.5- to 4.3-fold in patients with psoriasis when compared to patients providing normal skin samples." (PMID 37686332, 2023). "Among these inflammasomes, the NLRP3 inflammasome is the most studied, and is correlated to many inflammatory diseases such as psoriasis." (PMID 37686332, 2023). "The activation of LPAR5 on immune cells was related with NLRP3 inflammasome activation during psoriasis development." (PMID 36837912, 2023). "In addition, we found that the overall expression of NLRP3, ASC, IL-1β and caspase-1 is higher in the peripheral blood of psoriatic patients compared to normal controls, implying that overactivation of the NLRP3 inflammasome may also contribute to psoriasis-associated inflammatory responses." (PMID 36293012, 2022). "Below, we highlight recent reports that suggest a link between activation of NLRP3 inflammasome in psoriasis patients with possible consequent release of pro-inflammatory cytokines in these psoriasis patients." (PMID 35663672, 2022). "It is probably that AP-1 binding induces DDX3X expression, further activates NLRP3 inflammasomes to mediate psoriasis, and leads to lymphocyte infiltration in psoriatic lesions." (PMID 35277199, 2022). "Accumulating evidence demonstrates the role of NLRP3 in psoriasis patients, with potential reductions in disease activity and fatigue from mediating pro-inflammatory cytokines (e.g., IL-1β and TNF-alpha) regulated by the NLRP3 inflammasome." (PMID 35663672, 2022). "Then, we found that the MS15 procedure promoted resilience to behavioral deficits in female mice with psoriasis: microglial activation and the NLRP3 pathway were inhibited, and CRMP2 and α-tubulin were increased in the MS15 mice." (PMID 36138986, 2022). "We demonstrate that DMF, an approved clinical treatment for relapsing–remitting multiple sclerosis and psoriasis, was an effective NLRP3 inhibitor in both macrophages and microglia, as has been suggested previously." (PMID 35137954, 2022). "Numerous single nucleotide polymorphisms (SNPs) of NLRP3, which are mainly gain-of-function mutations, have been described, for example, in SLE, IBD, MS, RA and psoriasis." (PMID 36293012, 2022). "DDX3X is a central decision maker in the formation of NLRP3 inflammasomes, and NLRP3 plays a vital role in inflammatory skin diseases, including psoriasis." (PMID 35277199, 2022).
psoriasis (continued). "Most recently, research efforts have demonstrated that patients with psoriasis have increased expression of the NLRP3 inflammasome in plasma, along with caspase-1 reactivity and elevated inflammasome-generated IL-1β and IL-18 concentrations." (PMID 35663672, 2022). "Two NLRP3 SNPs (rs3806265 and rs10754557) were found to be significantly related to psoriasis in a Han Chinese population." (PMID 33925158, 2021). "In the psoriasis samples, the expression of NLRP3 was four times higher than the expression of NLRP3 in normal skin biopsy samples." (PMID 34072753, 2021). "Treatment with TLR-7, -8, and -9 antagonists in these mice was shown to reduce both psoriasis-related skin lesions, inhibit the dermal expression of NLRP3 and AIM2, and decrease the secretion of Th1 and Th17 cytokines in the skin and serum." (PMID 34072753, 2021). "In psoriasis biopsy, the expression of NLRP3, caspase-1, and IL-1β was significantly upregulated compared to non-lesional psoriatic skin." (PMID 34707607, 2021). "In mouse model of psoriasis, NLRP3 inflammasome keratinocytes can be activated by TNF-α to induce inflammation, which was induced by inhibiting autophagy via PI3K/AKT/mTOR signaling pathway." (PMID 34707607, 2021). "Xenobiotics such as alum, silica, and imiquimod, which is used for the induction of psoriasis-like-inflammation in the mouse modelcan also activate NLRP3." (PMID 34502368, 2021). "Recently, lysophosphatidic acid (LPA)/LPAR5 signaling has been reported to be involved in both NLRP3 inflammasome activation in macrophages and keratinocyte activation to produce inflammatory cytokines, contributing to psoriasis pathogenesis." (PMID 34639115, 2021). "It is noteworthy that LPAR5 can activate NLRP3 inflammasome in macrophages and contribute to imiquimod-induced psoriasis-like lesions." (PMID 34662522, 2021). "Abnormally activated immune response is key to psoriasis development and, therefore, in psoriasis, the role of NLRP3 inflammasome activation received extensive curiosity and appreciation." (PMID 34072753, 2021). "Co-treatment with BAY 11-7082 (a NF-κB inhibitor) attenuated psoriasis, along with reduced expressions of p-NF-κB, NLRP3, IL-1β, TNF-α, and IL-6." (PMID 33912556, 2021). "Though NF-κB is a powerful activation regulator of NLRP3, the contribution of NLRP3 inflammasome to imiquimod-induced psoriasis remains controversial considering the broad ant-inflammatory activity of BAY 11-7082." (PMID 33912556, 2021). "Inflammasome genes are highly upregulated in psoriatic epidermis and the evidence collected here points out the roles of AIM2 an NLRP3 in the pathogenesis of psoriasis and its systemic manifestations." (PMID 34502368, 2021). "The microneedle can be internalized by keratinocytes and immune cells, and disrupted NLRP3 inflammasome selectively to alleviate skin inflammations in a mouse model of psoriasis." (PMID 34707607, 2021). "It is worthy of note that LPAR5 can activate NLRP3 inflammasome in macrophages and contribute to imiquimod-induced psoriasis-like lesions." (PMID 34662522, 2021). "The study shows that patients with psoriasis have increased plasma levels of IL-1β and IL-18 and increased constitutive expression of the inflammasome sensors NLRP3, NLRP1, and AIM2 in peripheral blood cells, together with increased caspase 1 reactivity." (PMID 34502368, 2021). "The bound of soluble CD100 to PlxnB2 can upregulate NF-κB pathway, which induces NLRP3 inflammasome activation in keratinocytes of psoriasis patients." (PMID 34707607, 2021). "A recent study reported that BAY 11-7082, an antagonist of NF-κB, can alleviate psoriasis-like dermatitis by inhibiting the NLRP3 inflammasome and the NF-κB pathway." (PMID 32528469, 2020). "Most of F4/80-immunopositive cells were overlapped with NLRP3-immunopositive cells in the dermis, indicating that NLRP3 upregulation in psoriasis lesion mainly occurred in macrophages." (PMID 32707926, 2020).
psoriasis (continued). "Reportedly, the axonal guide molecules, CD100 and Plexin-B2, are involved in the inflammatory process of psoriasis by activating NF-κB and NLRP3 inflammasome in keratinocytes." (PMID 32377228, 2020). "SFAs, red meat, simple sugars, or alcohol exacerbate psoriasis and its comorbidities via the activation of NLRP3 inflammasome cascade or TNF-α/IL-23/IL-17 axis, generation of ROS, prostanoids/LTs, gut dysbiosis or suppression of Tregs." (PMID 32751360, 2020). "NLRP3 expression is increased in psoriasis lesion of both human patients and experimental rodent models." (PMID 32707926, 2020). "Clinical datasets of renal cell carcinoma and psoriasis patients showed a positive correlation between enzymes affecting the S1P rheostat with NLRP3 inflammasome components expression, which corroborates our finding." (PMID 32630814, 2020). "IMQ application significantly increased the number of NLRP3-immunopositive cells mainly in the dermis of psoriasis lesion." (PMID 32707926, 2020). "In particular, activation of LPA5 signaling was found to upregulate macrophages NLRP3 expression in psoriasis lesions." (PMID 32707926, 2020). "Various factors (microRNAs [miRNAs], genes, drugs) have been reported to activate or inhibit the NLRP3 inflammasome in cultured human keratinocytes or mice with IMQ-induced psoriasis." (PMID 32528469, 2020). "Ample evidence had shown that NLRP3 was particularly activated in psoriasis, and it was expressed both in the inflammatory cellular infiltrate in the dermis and in the epithelial cells of the psoriatic epidermis." (PMID 31181689, 2019). "The imiquimod model of psoriasis in mice is characterized by increased protein expression of NLRP3 that positively correlated with miR-155 expression in skin lesions when comparted to unaffected skin." (PMID 31333659, 2019). "NLRP3, a key inflammasome component, plays a significant role in psoriasis development." (PMID 40405066, 2025). "The NLRP3 inflammatory corpuscle is an important inflammatory regulator that can promote the maturation and release of proinflammatory cytokines, such as IL-1β, after activation, thus aggravating the inflammatory state of psoriasis." (PMID 40430037, 2025). "Moreover, the therapeutic potential of modulating inflammasome pathways has gained traction, with several studies exploring NLRP3 inhibitors or IL-1β blockade in preclinical models of psoriasis and other chronic inflammatory diseases." (PMID 40771724, 2025). "Psoriasis skin samples had four times the expression of NLRP3 compared to healthy controls." (PMID 40606452, 2025). "Furthermore, select polymorphisms in NLRP3, as well as the related NRLP1, are associated with increased risk of psoriasis, potentially through increases in IL-1 or IL-18 which are known to be increased in psoriatic lesions." (PMID 40606452, 2025). "It is essential to underline that although P2X7R was previously studied in psoriasis and rosacea, it is not the sole method of NLRP3 activation." (PMID 38534777, 2024). "Activation of the NLRP3 inflammasome by macrophages can also be involved in psoriasis." (PMID 39148738, 2024). "The NLRP3 (rs10754558) genotypes GC was associated with the severe form of psoriasis and with nonresponse to psoriasis medication." (PMID 38965465, 2024). "The method of inhibiting NLRP3 inflammasome activation can alleviate psoriasis inflammation." (PMID 39148738, 2024). "The study revealed a significant association between the GC genotype of NLRP3 (rs10754558) with nonresponse to psoriasis medication." (PMID 38965465, 2024). "Evaluation of the NLRP3 gene polymorphism, the serum level of CRP and TNFα in psoriasis patients and assessment of the NLRP3 (rs10754558) gene polymorphism, CRP and TNFα with disease severity and their role as biomarkers for response to Methotrexate and Adalimumab in psoriasis." (PMID 38965465, 2024). "The NLRP3 inflammasome plays a crucial role in psoriasis, particularly in keratinocytes." (PMID 38892253, 2024).
psoriasis (continued). "Considering that multiple reports highlight the potential of NLRP3 inflammasome as therapeutic target for psoriasis, we wonder whether THL exerts a promising therapeutic effect on psoriasis by regulating NLRP3 inflammasome." (PMID 37506136, 2023). "THL may alleviate IMQ‐induced psoriasis‐like manifestations in mice by inhibiting NLRP3 inflammasome." (PMID 37506136, 2023). "Likewise, quinolinic acid, an AHR agonist derived from skin microbiota, negatively regulates NLRP3 inflammasome through the AHR-Trp pathway in Psoriasis." (PMID 37942478, 2023). "This suggests that D3T could be used to treat NLRP3-inflammasome-overactivation-induced diseases such as psoriasis." (PMID 37686332, 2023). "The results suggested that NLRP3 was expressed in some parts of the epidermal cells in the control group with weak staining, whereas NLRP3 was strongly expressed in the cytoplasm of the full‐thickness cells of the epidermis in the IMQ‐induced mouse psoriasis‐like model group." (PMID 37506136, 2023). "In the present study, we demonstrated that IMQ-induced psoriasis could induce NLRP3 and caspase-1 expression and be downregulated through D3T treatment." (PMID 37686332, 2023). "In this study, we aimed to investigate the effects of D3T in the treatment of psoriasis in imiquimod (IMQ)-induced psoriasis animal models, as well as the effect which D3T has on reducing proinflammatory cytokine expression through inhibiting NLRP3 inflammasome activation." (PMID 37686332, 2023). "Studies speculated that NLRP3 inflammasome has a role in the pathogenesis of IMQ‐induced psoriasis‐like lesions in mice, and THL may alleviate psoriasis‐like manifestations in mice by inhibiting NLRP3 inflammasome." (PMID 37506136, 2023). "In addition, the inflammatory milieu can also further aggravate psoriasis through activation of NLRP3." (PMID 37443800, 2023). "Although the complexity of the NLRP3 inflammasome is emerging within the context of psoriasis and fatigue, significant gaps in our understanding of the specific regulatory mechanisms governing the pathology of psoriasis and its association with the NLRP3 inflammasomes remain." (PMID 35663672, 2022). "As such, the modulation of NLRP3 inflammasome in psoriasis patients may be responsible for patient-reported fatigue symptoms." (PMID 35663672, 2022). "Along this line, genetic data have also indicated an association with polymorphism in NLRP1, NLRP3, and AIM2 in psoriasis, and more recently, the association with a genetic polymorphism in inflammasome-related genes has been shown in patients with psoriatic arthritis." (PMID 34502368, 2021). "NLRP3 has been described to have indispensable role in the pathogenesis of numerous skin diseases, including acne, atopic dermatitis, urticaria (or hives), bullous pemphigoid, vitiligo and psoriasis." (PMID 33925158, 2021). "Therefore, further exploration and verification is required to clarify the relevance between NLRP3 inflammasome and psoriasis." (PMID 34072753, 2021). "Another group of researchers from China showed that the combination of PlxnB2 and its soluble ligand, CD100, stimulates the production of IL-1β and IL-18 by keratinocytes and activates the NLRP3 inflammasome and the NF-kB pathway during the course of psoriasis." (PMID 34072753, 2021). "Furthermore, recent studies found that BAY 11-7082 is considered an antagonist of causes, not only the activation of NF-kB, but it can also alleviate psoriasis-like dermatitis by inhibiting the NLRP3 inflammasome and the NF-kB pathway." (PMID 34072753, 2021). "All these findings indicate that NLRP3 inflammasome may be involved in the occurrence and development of psoriasis." (PMID 34707607, 2021). "Moreover, MCC950, a recognized NLRP3 inflammasome inhibitor, can significantly alleviate imiquimod-induced psoriasis-like dermatitis." (PMID 34072753, 2021). "It is confirmed that the NLRP3 inflammasome formation may contribute to psoriasis inflammatory response." (PMID 34072753, 2021).